SMAD1 (SMAD family member 1)
Diseases named in the same sentence as SMAD1 in open-access papers (continued):
Sharing a sentence is not in itself a finding about the gene and the disease.
atherosclerosis (13 papers, 2013 to 2025). A disease characterized by the build-up of fatty material and calcium deposition in the arterial wall resulting in partial or complete occlusion of the arterial lumen. "A recent study has illustrated that circCOL1A1 promotes the phenotype switch of vascular smooth muscle cells (VSMCs) via miR-30a-5p/Smad1/TGF-β axis in atherosclerosis." (PMID 37940881, 2023). "Our results showed that PPP and PU exert protective effects on the arterial wall and atherosclerosis by attenuating disturbed flow/inflammation-induced vascular dysfunction, mainly through suppressing force-specific activation of Smad1/5 in ECs." (PMID 34262908, 2021). "BMP4 accelerate the progression of atherosclerosis by induced macrophage foam cell formation through BMPR-2/Smad1/5/8 signaling." (PMID 31064817, 2019). "There is evidence indicating that BMP antagonists and signaling pathway inhibitors block activation of SMAD1/5/8 signaling, and thereby reduce the incidence of subsequent events, including vascular inflammation and atherosclerosis." (PMID 24107300, 2013). "Increased SMAD1 expression leads to decreased levels of the cholesterol transporters ABCA1 and ABCG1, with lipid accumulation by macrophages producing foam cells that are associated with atherosclerosis." (PMID 37164635, 2023). "Our previous studies also demonstrated that disturbed flow-induced activation of Smad1/5 can promote EC cell cycle progression and proliferation, which may contribute to the formation and progression of atherosclerosis." (PMID 34262908, 2021). "Since depletion of Caveolin-1 leads to a reduction of SMAD1/5, Caveolin-1, rather than ALK1 or BMP9, could be an interesting target for the treatment of vascular diseases, especially in early atherosclerosis." (PMID 36171573, 2022).
melanoma (13 papers, 2012 to 2024). A malignant, usually aggressive tumor composed of atypical, neoplastic melanocytes. "BMP7 acting via ALK2 and SMAD1/5 has been shown to induce the MET in melanoma cells and inhibit metastasis." (PMID 36289908, 2022). "Our previous in vitro results demonstrated that baohuoside-I inhibited melanoma cell proliferation and invasion via up-regulation of miR-144 and in turn down-regulation of SMAD1." (PMID 29260980, 2018). "In order to understand the clinical significance of the TGF-β transcriptional network in malignant melanoma, we analyzed expression levels of the SMADs (SMAD1–5) and of the adaptor CITED1." (PMID 26526369, 2015). "Consequently, the transition from promoting invasiveness to inducing apoptosis in melanoma cells is likely unrelated to the phosphorylation of SMAD1/5." (PMID 39709491, 2024). "In this study, our data indicate the IL-1β stimulation could enhance the stemness of HNSCC and melanoma cells through activating Smad1/5/8 and ID1 signaling pathway." (PMID 32547321, 2020). "Moreover, clinical sample collected from melanoma patients manifested a reverse correlation between miR-144 and SMAD1, which further consolidated our in vitro data." (PMID 29260980, 2018). "As the cytoplasmic portion of CD44 interacts with Smad1 in chondrocytes, and promotes phosphorylation of Smad1 and Smad4 and their nuclear translocation, it is likely that a similar mechanism underlies the BMPR co-receptor function for CD44 in melanoma cells." (PMID 30297743, 2018). "This could involve TGFβ as well as BMP signaling, as in Ewing sarcoma and melanoma cell lines endoglin was shown to lead also to higher BMP induced Smad1 phosphorylation." (PMID 23088614, 2012). "Along with targeting other oncogenic target genes such as SODD, SMAD1, and MAP4K3, miR-26a inhibited the growth of melanoma cells by directly downregulating MITF." (PMID 28698805, 2017). "This hypothesis was driven, in part, by our previous data in human melanoma cells, in which knockdown of GDF6 decreased phospho-SMAD1/5/8 binding at the MITF locus and increased MITF expression." (PMID 31868592, 2019). "On the other hand, FAD104 inhibited the phosphorylation level of STAT3, whereas FAD104 had no influence on the Smad1/5/8 phosphorylation in A375 melanoma cells." (PMID 29180690, 2017).
glioma (12 papers, 2012 to 2025). A benign or malignant brain and spinal cord tumor that arises from glial cells (astrocytes, oligodendrocytes, ependymal cells). "Although BMP signaling can inhibit growth in normal neuroepithelial cells, SMAD1 activation in gliomas has been linked to mesenchymal transformation and enhanced plasticity." (PMID 40869118, 2025). "Samples with significant SMAD1 transcriptional expression were further characterized into different glioma datasets." (PMID 39629919, 2025). "It was revealed that SMAD1 was highly expressed in gliomas, covering different histology, grades, and subtypes." (PMID 39629919, 2025). "An overview of TCGA RNA‐seq data derived from the Human Protein Atlas revealed that gliomas had the highest SMAD1 transcriptional expression among cancers." (PMID 39629919, 2025). "Overexpression of FSTL1 has been identified as an indicator of an unfavorable prognosis in GBM patients, with research indicating that Fstl1 stimulates glioma growth via the BMP4/Smad1/5/8 signaling pathway." (PMID 40781854, 2025). "Treating cells with DAPT increased Smad1/5 phosphorylation within 0.5 h of treatment in LN18 glioma cells, with phosphorylation peaking within 1 h and returning to basal levels after 4 h of treatment." (PMID 34104086, 2021). "Our present study showed that Smad1/5 phosphorylation in LN18 glioma cells only persists for ~4 h after DAPT stimulation." (PMID 34104086, 2021). "LN18 glioma cells were pretreated with control (siCL), Smad1 (siSmad1)-, or Smad5 (siSmad5)-specific siRNAs and then were kept as controls or treated with 80 μM DAPT for 48 h." (PMID 34104086, 2021). "Information about a potential role for Smad1/5 activity upregulation and subsequent E-cadherin downregulation during inhibition of γ-secretase activity in the development of gliomas is therefore relevant for future research." (PMID 34104086, 2021). "(iii) endogenous Smad1 plays a critical role in E-cadherin expression and consequent migration of glioma cells." (PMID 34104086, 2021). "LN18 glioma cells were pretreated with control (siCL), Smad1 (siSmad1)-, or Smad5 (siSmad5)-specific siRNA and then were kept as controls or treated with 80 μM DAPT for 48 or 96 h and then cell migration was examined by chemotaxis and wound-healing methods." (PMID 34104086, 2021). "In the clinical studies, the role of Smad1 expression and activation in the cell fate regulation of glioma is still unclear." (PMID 34357080, 2021). "The overexpression of BMPR1B activated the BMPs/Smad1/5/8 signaling pathway and inhibited the growth of glioma cells through various mechanisms, including the decrease of SKP2 expression, followed by the increase of p21 and p27kip1 Protein Expression35." (PMID 33116227, 2020). "Moreover, endogenous Smad1 in glioma cells was found to play an important role in regulating E-cadherin expression and subsequent cell migration but did not affect DAPT-stimulated effects." (PMID 34104086, 2021). "This suggests that endogenous Smad1 may have a regulatory role in glioma cells." (PMID 34104086, 2021). "BMP and Smad1/5 signaling may play important roles in glioma development 22, 25-26." (PMID 34104086, 2021). "Importantly, overexpression of BMPR-IB activated the BMPs/Smad1/5/8 signaling pathway and clearly inhibited the growth of glioma cells through multiple mechanisms, including decreased expression of Skp2, and subsequently increased the expression of the p21 and p27Kip1 proteins." (PMID 22650359, 2012). "Fstl1, a member of the family, is elevated in high‐grade gliomas and contributes to tumor growth via the BMP4/Smad1/5/8 pathway." (PMID 40781854, 2025). "Cells pretreated with Smad1-specific siRNA decreased the basal migration level in DAPT-untreated cells, and the DAPT treatment also further promoted LN18 glioma cell migration." (PMID 34104086, 2021). "LN18 glioma cells were kept as controls or treated with 80 μM DAPT for 0.5 h, 1 h, 4 h, 8 h, or 24 h and then Smad1/5 phosphorylation were examined." (PMID 34104086, 2021).
glioma (continued). "Additionally, we found that endogenous Smad1 may have a regulatory role in glioma cells." (PMID 34104086, 2021). "For instance, the TGF-β signaling pathway was found to be altered through glioma progression, as observed by an increase in the level of BMP molecules, including BMP3 and BMP4, as well as their targets, such as Smad1/5/8 and Id." (PMID 33671331, 2021). "Overall, we observed 956 genes differentially expressed between the SMAD1(+) and SMAD2(+) glioma cell populations (Bonferroni-adjusted P < 0.05); 671 genes were upregulated in SMAD2+ cells, while 285 were upregulated in SMAD1(+) cells." (PMID 31602000, 2019). "The western blot results also demonstrated reduced basal levels of Smad-1, Smad-3 and TGF-β proteins in miR-211 and IR-treated cells when compared to control glioma CSC." (PMID 23183822, 2012). "(ii) This DAPT/RO4929097 effect on glioma cells is regulated by BMPs-independent Smad5 (not Smad1) activation." (PMID 34104086, 2021). "In addition, cells pretreated with Smad1-specific siRNA increased the basal endoenous E-cadherin protein and mRNA expressions in DAPT-untreated cells, and the DAPT treatment also further downregulated E-cadherin expressions in LN18 glioma cells." (PMID 34104086, 2021). "Moreover, Kaplan-Meier survival curves and log-rank analysis showed that patients with a low P-Smad1,5,8/total Smad1,5,8 ratio had statistically shorter survival times, reinforcing the negative correlation between P-Smad/BMPRIB and the malignant grade of glioma." (PMID 24877113, 2014). "Moreover, our findings indicate that although Smad1 is not involved in regulating DAPT inhibition of E-cadherin expression, basal endogenous Smad1 levels can regulate E-cadherin expression and subsequent glioma cell migration." (PMID 34104086, 2021).
lung carcinoma (12 papers, 2011 to 2025). "The results suggest that BMP2-BMPR2 binding induces cell migration and invasiveness through the activation of the SMAD1/5 pathway in lung cancer cells." (PMID 36175474, 2022). "Dorsomorphin (DM), a specific SMAD1 inhibitor, prevents SMAD1 phosphorylation, leading to suppression of lung cancer cell growth." (PMID 34134766, 2021). "Evidence suggests that SMAD family member 1 plays an integral role in different cancer types, such as lung cancer and colorectal cancer." (PMID 33336042, 2020). "In this study, we showed the prognostic significance of FSTL1-BMP4-p-Smad1/5/8-Smad4 pathway in lung cancer with histological specificity." (PMID 28852126, 2017). "Further investigations have revealed that the inhibitory effect of RGMB in lung cancer is occurs primarily through suppression of the Smad-1/5/8-dependent pathway." (PMID 26910889, 2016). "In general, an overall positive correlation was observed between the expression of LKB1 and phospho-Smad1/5/8 (r = 0.39; p < 0.01) when all lung cancer histologic subtypes were included in the analysis." (PMID 26701726, 2016). "While the possible contribution of the p38 MAPK pathway merits further studies it should be emphasized that this pathway may converge with the canonical Smad pathway through its activation of Smad1, as shown in lung cancer cells." (PMID 35518645, 2022). "Blocking Smad1 in RGMB-knockdown A-549 cells diminishes the RGMB knockdown-enhanced migration of these cells suggesting that RGMB can inhibit the metastatic potential of lung cancer cells through suppression of the Smad-1/5/8 pathway." (PMID 26910889, 2016). "Moreover, lung cancer metastasis is inhibited by CYP3A5 through regulation of the ATOH8/Smad1 axis." (PMID 39754188, 2025). "Other genes targeted by miR-26a include SMAD1 which is related to osteogenic differentiation of human adipose tissue stem cells, and PTEN which is related to metastases in lung cancer cells." (PMID 33843426, 2021). "To evaluate the importance of FSTL1-BMP4-Smad pathway in lung cancer, we first analyzed the prognostic value of FSTL1, BMP4, Smad4, and p-Smad1/5/8." (PMID 28852126, 2017). "In a lung cancer cell-line model, p38 MAPK activation was required for full activation of the transcriptional potential of Smad1/5, after treatment with BMP-4." (PMID 22299030, 2012).
diabetic nephropathy (11 papers, 2011 to 2025). "Smad1/mTOR signaling transduction is involved in autophagy dysfunction-mediated podocyte injury, and hyperactivation of mTOR in diabetic nephropathy plays a fundamental role in podocyte injury." (PMID 38988671, 2024). "Our previous study provided evidence supporting involvement of the BMP-2/Smad1/Runx2/Osterix signaling pathway in the development of vascular calcification in diabetic nephropathy rats." (PMID 29850574, 2018). "We previously reported that AngII activates the c-Src/Smad1 signaling pathway in the development of diabetic nephropathy and cultured MCs." (PMID 21445358, 2011). "Additionally, exosomes containing miR-486 secreted by adipose-derived stem cells (ADSCs) have been shown to enhance autophagic flux in podocytes by inhibiting Smad1/mTOR signaling, thereby ameliorating diabetic nephropathy." (PMID 41390431, 2025). "In 2019, his group reported that ADSC-exosomes improved diabetic nephropathy symptoms by increasing the expression of miR-486, which led to the inhibition of the Smad1/mTOR (Mothers Against Decapentaplegic family 1/Mammalian target of rapamycin) signaling pathway in podocytes." (PMID 38988671, 2024). "NCF1, OSM, SMAD1 and TGFB1 provide protection against diabetic nephropathy, SYVM1 and TXNIP protect against diabetic retinopathy and BDNF in ameliorating the diabetic neuropathy." (PMID 28761062, 2017). "In this review, we focus on the early glomerular and tubular structural alterations, with a detailed description of the glomerular injury markers SMAD1 and Podocalyxin, and the tubular injury markers NGAL, Netrin-1, and L-FABP in the context of diabetic nephropathy." (PMID 36425298, 2022). "Similarly, other studies have also shown that in experimental diabetic kidney disease (DKD) Lrg1 gene expression induced in glomerular endothelial cells is involved in vascular rarefication and subsequent neovascularization and fibrosis, partly via activation of the p38 and TGF-β-SMAD1/5/8 pathway." (PMID 38745756, 2024).
osteoporosis (11 papers, 2019 to 2023). A condition of reduced bone mass, with decreased cortical thickness and a decrease in the number and size of the trabeculae of cancellous bone (but normal chemical composition), resulting in increased fracture incidence. "Rhizoma cibotii strengthens bones and tendons and treats osteoporosis by activating the BMP2/SMAD1 signaling pathway for osteogenesis." (PMID 38114998, 2023). "Collectively, Runx1 maintains adult bone homeostasis from bone loss though up-regulating Bmp7/Alk3/Smad1/5/8/Runx2/ATF4 and WNT/β-Catenin signaling pathways, and targeting Runx1 potentially leads to novel therapeutics for osteoporosis." (PMID 33476325, 2021). "BM cells from the femurs and tibias of recipient mice injected with SM-EVs (from patients with tryptase >110 ng/ml) or SM-EVs from patients with osteopenia/osteoporosis showed markedly reduced mRNA expression levels of Alp, Runx2, Smad1/5, and to a lesser extent Smad2." (PMID 33953168, 2021). "The authors verified the potential anti-osteoporotic effects of apple-derived nanovesicles using MC3T3-E1 cells, inhibiting osteoporosis by promoting osteoblastogenesis in osteoblastic MC3T3-E1 cells, by regulating the BMP2/Smad1 pathway." (PMID 37109395, 2023). "The present study also demonstrated that vitamin C enhanced the expression of the osteoblast-specific genes, BMP-2, SMAD1/5/8, RUNX2, osteocalcin, and COL-1, in an in vivo model of osteoporosis." (PMID 30818817, 2019). "Runx1 maintained adult bone homeostasis and bone differentiation though upregulating Bmp7/Alk3/Smad1/5/8/Runx2/ATF4 and WNT/β-Catenin signaling pathways, suggesting that targeting Runx1 might be a novel therapeutics for osteoporosis." (PMID 37156809, 2023). "In conclusion, interference with METTL14 inhibited osteogenic differentiation of BSMCs by m6A modification of SMAD1 in an IGFBP1 manner, suggesting that METTL14 might be a novel approach for improving osteoporosis." (PMID 36319624, 2022). "Treatment of Western diet-fed ovariectomized ApoE−/− mice (presenting both advanced atherosclerotic calcification and osteoporosis) with E2 inhibited osteoporosis and the BMP osteogenic pathways in aortas by decreasing SMAD1/5/8 phosphorylation, thus leading to reduction in calcium accumulation." (PMID 34204304, 2021). "In addition, taurine increased the expression levels of BMP-2, Wnt3a, SMAD1/5/8, RUNX2, and COL-1 in the in vivo osteoporosis model and stimulated the p-Akt, p-p38, p-JNK, and p-ERK signaling pathways." (PMID 31970094, 2019). "Moreover, Western blotting revealed enhanced phosphorylation of Smad1/5/8, which confirmed the activation of BMP/Smad signaling in KO mice in osteoporosis." (PMID 30787286, 2019).
ovarian carcinoma (11 papers, 2012 to 2025). A malignant neoplasm originating from the surface ovarian epithelium. "Altered BMP signalling in ovarian cancer was also observed in epithelial ovarian cancer cells since autocrine BMP9, which usually signals through ACVRL1, also signals through ACVR1, increasing the phosphorylation of SMAD1/5 and promoting ovarian cancer cell proliferation." (PMID 31683698, 2019). "Deletions of Smad1 and Smad5 lead to infertility and ovarian cancer in mice." (PMID 22496700, 2012). "For example, overexpression of SMAD1 induces proliferation in stomach cancer cells in response to BMP-7 stimulation, and upon activation by BMP-9, SMAD1 promotes ovarian cancer cell growth." (PMID 34134766, 2021). "Surprisingly, even though the main signalling pathway SMAD1/5 is shared, BMP or AMH can either promote or inhibit ovarian cancer cell proliferation." (PMID 31683698, 2019). "Another example of the involvement of the TGFβ family in ovarian cancer development is BMP/SMAD1/5/8 signaling, whereby double SMAD1 and SMAD5 or triple SMAD1, 5 and 8 conditional knockout in mice generates metastatic granulosa cell tumors." (PMID 28758950, 2017). "In ovarian cancer, SMAD1 positively regulates SOX2 and SMAD3 negatively regulates SOX2, which acts as a regulatory node that controls the signalling of the TGF-β pathway, which in turn affects ovarian cancer metastasis." (PMID 37685308, 2023).